LINC01013 (long independently transcribed non-coding RNA 1013)
Synonyms: AERRIE; LINC01013ORF; LINC02921
Gene: Long non-coding RNA gene on chromosome 6 (131,901,797 to 132,169,995, forward strand). Ensembl gene ENSG00000228495.
Diseases named in the same sentence as LINC01013 in open-access papers:
LINC01013 is named in the same sentence as 11 diseases in open-access papers, as found by Europe PMC text mining. Sharing a sentence is not in itself a finding about the gene and the disease. The quoted sentences say what the papers report.
anaplastic large cell lymphoma (3 papers, 2020 to 2026). Anaplastic large cell lymphoma (ALCL) is a rare and aggressive peripheral T-cell non-Hodgkin lymphoma, belonging to the group of CD30-positive lymphoproliferative disorders, which affects lymph nodes and extranodal sites. "LINC01013 enhances the invasion of anaplastic large-cell lymphoma by activating of the epithelial-to-mesenchymal transition." (PMID 33221763, 2020).
acute myeloid leukemia (1 paper, 2020). Acute myeloid leukemia (AML) is a group of neoplasms arising from precursor cells committed to the myeloid cell-line differentiation. "Notwithstanding, LINC00152 and LINC01013 expression have been correlated with poor prognosis in diverse human cancer types, including acute myeloid leukemia, supporting the potential role of both genes in ALL as risk predictors of poor outcomes." (PMID 32183133, 2020).
hepatocellular carcinoma (1 paper, 2022). A malignant tumor that arises from hepatocytes. "A previous study found that LINC01013 directly bound to miR-6795-5p and subsequently relieved FMNL3 in hepatocellular carcinoma cells." (PMID 35449053, 2022).
leukemia (1 paper, 2025). A malignant (clonal) hematologic disorder, involving hematopoietic stem cells and characterized by the presence of primitive or atypical myeloid or lymphoid cells in the bone marrow and the blood. "As expected, several previously reported genes with abnormal methylation in leukemias such as CPEB1, BLK, FLT3, ZCCHC7, EBF1, HDACs, IKZF1, RB1, CDK6, DOCK5, DPP10, MUC4, JAKs, KIT, KRAS, LINC01013, MAD1L1, NOTCH1, and STATs, among others, were also detected." (PMID 41226303, 2025).
tumor (3 papers, 2017 to 2024). "Taken together, these data confirm the requirement of LINC01013 to accelerate tumor cell invasion and implicate the snail-fibronectin cascade in this process." (PMID 28331184, 2017). "Knockdown of LINC01013 suppressed tumor cell invasion; conversely, its overexpression enhanced tumor cell invasion." (PMID 28331184, 2017). "Moreover, loss- and gain-of-function experiments revealed that LINC01013 could promote HCC cell proliferation and tumor progression by enhancing stemness of cells both in vitro and in vivo." (PMID 38568288, 2024). "LINC01013 was over-expressed in ALCL in comparison with adjacent noncancerous, and in vitro studies demonstrated that its up-regulation enhanced tumor cell invasion through the induction of snail-fibronectin activation cascade." (PMID 32183133, 2020).
cancer (2 papers, 2017 to 2020). A tumor composed of atypical neoplastic, often pleomorphic cells that invade other tissues. "Collectively, these results support a potential role of LINC01013 in promoting cancer cell invasion through activation of the snail-fibronectin cascade in ALCL." (PMID 28331184, 2017). "The discrepancies between both studies could be explained by a dual (oncogene and gene suppressor) role of LINC01013 in cancer." (PMID 32183133, 2020). "Collectively, these findings support a potential role for LINC01013 in cancer cell invasion through the snail-fibronectin activation cascade and suggest that LINC01013 could potentially be utilized as a metastasis marker in ALCL." (PMID 28331184, 2017). "Since LINC00152 and LINC01013 have been reported as relevant in the hematopoiesis processes and that both genes exhibited co-expression with coding genes that have been reported as cancer-related, the expression of both genes was used to evaluate their clinical significance." (PMID 32183133, 2020).
metabolic disorders (1 paper, 2026). "We confirmed that LINC01013 as a protein-binding scaffold connecting HSPA9 and VDAC1, contributing to the oligomerization of VDAC1 and mitochondrial dysfunction including oxidative stress and metabolic disorders, and ultimately hypoxic PH progression." (PMID 41491061, 2026).
LINC01013 also shares sentences with these, for which no sentence is quoted: acute leukemia (1 paper); calcific aortic valve disease (1); hematological malignancies (1); Myocardial fibrosis (1).